COL1A2 (collagen type I alpha 2 chain)
Diseases named in the same sentence as COL1A2 in open-access papers (continued):
Sharing a sentence is not in itself a finding about the gene and the disease.
osteogenesis imperfecta (continued). "Osteogenesis imperfecta (OI), also known as brittle bone disease, is a disorder of connective tissue typically featured by fragile bones and susceptibility to fracture, mostly (~ 90%) caused by autosomal dominant pathogenic variants in the COL1A1 and COL1A2 genes, which encode type I collagen." (PMID 35463886, 2022). "This initial screening allowed us to identify families with osteogenesis imperfecta (caused by COL1A1 and COL1A2 mutations), as well as mutations in the non-repetitive regions of DSPP." (PMID 35627243, 2022). "In this case report, we reported a male infant with twenty-three intrauterine/fetal fractures resembling osteogenesis imperfecta and tested negative for COL1A1 and COL1A2 mutations." (PMID 34204301, 2021). "Osteogenesis imperfecta (OI) is a phenotypically and genetically heterogeneous group of bone disorders characterized by bone fragility and skeletal deformity, owing to the abnormality of type I collagen formed by two α1(I) chains (encoded by COL1A1 gene) and one α2(I) chain (encoded by COL1A2 gene)." (PMID 31680973, 2019). "The identification of human genes associated with bone fragility started around the 1990s through the study of monogenic syndromes with marked skeletal phenotypes such as osteogenesis imperfecta due to COL1A1 and COL1A2 defects and osteopetrosis due to TCIRG1 defects." (PMID 27533615, 2016). "However, in the severe mouse model of osteogenesis imperfecta (OIM), deletion of the COL1A2 gene results in the substitution of the α2(I) chain by one α1(I) chain." (PMID 26468064, 2015). "Osteogenesis imperfecta (OI) is known as brittle bone disease and is a rare, chronic, and currently noncurable disease characterized by inadequate formation of bone tissue due to a lack of collagen (mainly Col1A1 and Col1A2) or poor quality." (PMID 38459573, 2024).
liver fibrosis (61 papers, 2013 to 2025). "These genes are known to gradually increase upon NASH progression, with Gdf15 and Ccl20 encoding proinflammatory cytokines, Col1a1 and Col1a2 encoding collagen chain proteins, and Itgbl1 known for regulating liver fibrosis." (PMID 37914694, 2023). "In addition, a recent study reported that the COL1A2 gene is associated with liver fibrosis in mouse models, which can be associated with excessive deposition of ECM." (PMID 40489480, 2025). "Upon activation, HSCs transform into a fibroblastic phenotype, initiating massive synthesis of COL1A2 which deposits into the ECM to form nodular structures characteristic of hepatic fibrosis." (PMID 41306725, 2025). "A recent study suggests that Yap/Taz deletion with Col1a2-CreER attenuates bleomycin-induced lung injury and CCl4-induced liver fibrosis." (PMID 40454481, 2025). "The body reduces liver fibrosis through downregulating the expression of Col1a1 and Col1a2, thereby affecting the PI3K/AKT signaling pathway to induce HSC senescence." (PMID 40243656, 2025). "Collagen is a triple helical protein that is composed of 2 COL1A1 (α1) chains and 1 COL1A2 (α2) chain, and increased collagen synthesis by activated myofibroblasts is a major contributor to liver fibrosis." (PMID 39656528, 2024). "Treatment with α4β7 mAb reduced hepatic fibrosis reflected by decreased collagen deposition in the liver and significant reduction in the transcript levels of Acta2, Col1a1, Col1a2, Tgfb1 and Timp1." (PMID 38727292, 2024). "In this study, our steatohepatitis model demonstrated a rapid progression of hepatic fibrosis, even at 8 weeks, and pemafibrate completely suppressed Col1a1, Col1a2, and Ccl5 mRNA, which are involved in fibrosis." (PMID 35194060, 2022). "Other genes include connective tissue growth factor (CTGF) and four members of the collagen alpha chain family including COL1A2 which is also abundant in liver fibrosis." (PMID 32463444, 2020). "Our study also confirmed the elevation of fibrosis related gene expression, including αSMA and Col1A2 in HFHC-induced hepatic fibrosis." (PMID 32317687, 2020). "The expression of COL1A2, COL3, and TIMP-1 mRNA, which encode proteins involved in hepatic fibrosis, was analyzed." (PMID 30673721, 2019). "The mRNA expression levels of α-SMA and Col1a2 were significantly increased after the development of CCl4-induced liver fibrosis." (PMID 27420058, 2016). "Despite the increase in fibrosis in LysM-Wls mice, mRNA levels of the key interstitial collagens contributing to liver fibrosis, Col1a1, Col1a2 and Col3a1, were comparable between LysM-Wls and littermate controls." (PMID 26473015, 2015). "Furthermore, the protein–protein interaction (PPI) network analysis based on the STRING database and GOIs provided insights into the functional relationships among key proteins in liver fibrosis, such as Col1a2, Col5a2, MMP9, Col4aa, Col27a1, and Col5a3." (PMID 38874114, 2024). "We validated that LWPE could reduce the expression of Col1a2 by Western blotting, suggesting that Col1a2 may be a potential effective target for the treatment of liver fibrosis." (PMID 36313326, 2022). "Furthermore, expression of marker genes for hepatic fibrosis (Col1a1, Col1a2, Tgfb) and the immune cell marker Cd11c was higher in liver of AHKO mice fed HFD." (PMID 33692445, 2021). "Suppressing COL1A1 and COL1A2 expressions might decrease the activation of HSCs and eventually prevent liver fibrosis." (PMID 26691002, 2015). "Additionally, considering the potential impact of using data from fibrotic samples on the results, analysis of HSCs using fibrosis markers Col1a1 and Col1a2 demonstrated a progressive worsening of liver fibrosis over time, indicating that the samples had not yet developed fibrosis." (PMID 40589742, 2025).
liver fibrosis (continued). "Thus, dampening COL1A2 expression might inhibit stellate cell activation, offering a potential preventive measure against liver fibrosis." (PMID 37893992, 2023). "Likewise, we could not detect lower gene expression of hepatic collagen I (Col1a1 and Col1a2) or other liver fibrosis-promoting genes such as Lox25 or Timp126 in any of the dose groups evaluated." (PMID 37816736, 2023). "However, we cannot exclude the possibility that miR-125b may promote liver fibrosis by enhancing Col1a1 and Col1a2 expression." (PMID 30195793, 2018). "Unexpectedly, SHS mice displayed reduced Col1a1 and Col1a2 expression, slightly lower PSR-staining intensity and significantly decreased liver collagen content on a liver fibrosis-inducing diet." (PMID 40475534, 2025). "In contrast, aged mice exhibited hepatic fibrosis, with increased collagen deposition and upregulation of genes related to fibrosis (Acta2, MMP2, TGF-ß1, and Col1a2), cirrhosis (CXCR4, SOX9, DCN, and MFAP4), and cancer (Bcl2, CDKN2a, c-Myc, and Fn1)." (PMID 39851554, 2025). "Among the genes, further analysis disclosed that the gene expression levels of TLR2, Col1a1, Col1a2, Col4a1, Col4a2, and Pdgfr-β were changed during the SCU anti-liver-fibrosis process, and qRT-PCR verified this result." (PMID 40243656, 2025). "Although this study revealed the potential mechanisms of BPA-induced MASLD and provided an in-depth exploration of the crucial roles of the PI3K/AKT signaling pathway, COL1A1, COL1A2, and IGF1 in hepatic fibrosis, several limitations remain." (PMID 41306725, 2025). "On the basis of transcriptomics and network pharmacology findings, genes connected with liver fibrosis and the PI3K/AKT signaling pathway, such as Col1a1, Col1a2, Col4a1, Col4a2, TLR2, and Pdgfr-β, were chosen for qRT-PCR validation." (PMID 40243656, 2025). "In arsenite-induced liver fibrosis, lncRNA-MALAT1 facilitates miRNA-26b regulation of COL1A2 expression, thereby activating human HSCs." (PMID 39044218, 2024). "The validation cohort showed GPC3 was negatively correlated with all liver fibrosis markers ACTA2, COL1A1, COL1A2, COL3A1 and ductular reaction markers KRT7 and KRT19, while SDC4 was positively correlated with ductular reaction index KRT19." (PMID 36816373, 2023). "Transcriptional levels of liver fibrosis markers (ACTA2, COL1A1, COL1A2, COL3A1) and ductular reaction markers (EPCAM, KRT7, KRT19) were significantly upregulated in BA." (PMID 36816373, 2023). "Firstly, liver fibrosis (marker as ACTA2, COL1A1, COL1A2, COL3A1), reflected by proliferation of myofibroblasts and collagen deposition, is associated with decreased native liver survival mostly." (PMID 36816373, 2023). "The inhibitory effect of α-mangostin on liver fibrosis markers was also demonstrated by the mRNA levels of α-SMA, col1a2, MMP2 and desmin." (PMID 37760177, 2023). "Since the formation of hepatic fibrosis is a complex process of multi-factor and multi-cell involvement, our findings also point to the possible involvement of VACN, COL1A1, COL1A2, LUM, and FBLN5 in the generation of fibrotic response from NAFL to NASH." (PMID 36329886, 2022). "This induces the deactivation of CAFs, with the consequent reduction in the secretion of ECM components (COL1A1, COL1A2, and FN1) and liver fibrosis." (PMID 36443822, 2022). "On the contrary, ecKOm/m LSECs expressed lower levels of Col1a2 (encoding Collagen type I) and Acta2 (encoding α-SMA), two prominent mesenchymal markers, compared to WT LSECs, suggesting that MKL1 deficiency in endothelial may alleviate EndMT in the context of liver fibrosis in vivo." (PMID 31776330, 2019). "The Q-PCR analyses showed that the mRNA levels of the liver fibrosis marker genes (α-SMA and Col1a2) were up-regulated in both male and female WT mice, while hepatic NPC2 was decreased." (PMID 27420058, 2016).
liver fibrosis (continued). "Ten DEGs including PDGFra, PDGFrb, PDGFb, PDGFd, COL1A1, COL1A2, COL5A2, ITGA5, THBS1 and IL1R1, closely related to liver fibrosis, were chosen for the real-time qRT-PCR analysis." (PMID 26691002, 2015). "HQD down-regulated the expressions of PDGFra, PDGFrb, PDGFb, PDGFd, COL1A1, COL1A2, COL5A2 and THBS1, and TGF-β and PDGF signaling pathways in the DMN-induced liver fibrosis in rats." (PMID 26691002, 2015). "Therefore, COL1A1 and COL1A2 are recognized as key molecular markers for MASLD fibrosis, and their expression levels can be used to assess hepatic fibrosis severity and predict therapeutic responses." (PMID 41306725, 2025). "In previous studies using murine models, the combined use of BCAAs attenuated liver fibrosis through inhibition of the TGF-β1 signaling pathway by downregulating several key pathway components, including SMAD-4, P-SMAD3L, TIMP-1, PDGFRβ, p-ERK, and COL1A2." (PMID 39495311, 2024). "The CCl4-induced liver fibrosis mouse model showed that the administration of α-mangostin significantly decreased the expression of the fibrosis markers (α-SMA, collagen-a2 (col1a2), desmin and matrix metalloproteinase-2 (MMP-2)) as well as attenuated hepatic collagen deposition and liver damage." (PMID 37760177, 2023). "Lastly, although prolonged MCD diet feeding of mice housed at Tn increased the hepatic expression of Col1a1 (p=0.02) and Col1a2 (p=0.01), such induction did not yield robust histological differences in hepatic fibrosis at the conclusion of the study." (PMID 36875069, 2023). "Furthermore, liver fibrosis was suppressed in the samples of F4MKO mice assessed by Sirius Red staining, along with the downregulation of key genes of fibrosis (Acat2, Col1a1, Col1a2, Timp2, and Tgfβ)." (PMID 37770480, 2023). "Combined with the GO, KEGG and Western blot results, COL1A2, ITGAV, TLR2, ACE, and PDGFRB may be potential targets for PE treatment of liver fibrosis." (PMID 36313326, 2022). "In addition, rottlerin treatment also suppressed TGFβ1-induced expression of ACTA2, COL1A1, COL1A2, and CCL2, the expression of which is greatly increased in HSCs of liver fibrosis patients." (PMID 32210801, 2020). "In line with the histological analysis, results from the mRNA expression of pro-fibrotic genes (including Acta2, Col1a1, Col1a2, and Tgfb1) further demonstrated that prophylactic but not therapeutic administration of OCA were effective against liver fibrosis." (PMID 31932588, 2020). "In addition, RT-PCR indicated that the mRNA levels of Col1a2 and α-Sma on an HFD were approximately the same in both substrains, confirming no marked difference in the progression of the hepatic fibrosis between the BL6J and BL6N mice in the HFD-induced NASH model." (PMID 30659241, 2019).
gastric cancer (52 papers, 1988 to 2026). A primary or metastatic malignant neoplasm involving the stomach. "COL1A2 has also been implicated in gastric cancer, colorectal cancer, prostate cancer, pancreatic cancer, and so on." (PMID 36246603, 2022). "Among the investigated collagens the expression of COL1A2 was only previously noted in gastric cancer where was associated with metastasis formation and advanced stages of the disease." (PMID 30583585, 2018). "In the present study, we found that COL1A1 and COL1A2 were overexpressed in gastric cancer and potent prognostic factors by showing their associations with an adverse prognosis in gastric cancer patients." (PMID 27894325, 2016). "We identified several genes, including FN1, COL1A2, THBS2, COL3A1, COL5A1, and BGN, which appear to be associated with poorer outcomes for stomach cancer patients." (PMID 38610959, 2024). "Similar results were also found in gastric cancer, in which the upregulated genes were COL1A2 and COL6A3 or COL6A3, COL3A1, and COL1A1." (PMID 38069077, 2023). "Col1a1, fga, fgg, f2r, col3a1, and col1a2 are the important genes of this pathway, which are upregulated in gastric cancer." (PMID 35650297, 2022). "Collagen factors COL1A1, COL1A2, and COL3A1 were often implicated in carcinogenesis or metastasis in a variety of tumor types, for instance breast cancer, gastric cancer, and cervical cancer." (PMID 36059672, 2022). "It has been reported that COL1A2 is upregulated in cancer and that it promotes the proliferation and invasion of various cancers, such as gastric cancer and pancreatic cancer." (PMID 35711921, 2022). "It has been demonstrated that the abnormal COL1A2 mRNA expression led to a worse prognosis of gastric cancer patients and enhances the proliferation of prostate cancer cell." (PMID 36057263, 2022). "Gastric cancer patients with high expression of COL1A2 had significantly lower survival rates than patients with COL1A2 low expression, P = 0.029." (PMID 34326374, 2021). "In gastric cancer, COL1A2 is positively correlated with lymphatic metastasis, and macrophages, which is consistent with our results in low-grade glioma (r = 0.333, P < 0.05)." (PMID 34815785, 2021). "COL1A2 was found to significantly promote gastric cancer cell proliferation, migration, apoptosis, and invasion." (PMID 34034744, 2021). "This study found that ITGB1 and COL1A2 are key genes in the development of gastric cancer and can be used as prognostic markers and potential new targets for gastric cancer." (PMID 34326374, 2021). "Compared with normal tissues adjacent to cancer, the expression of ITGB1 and COL1A2 in gastric cancer tissues were significantly increased." (PMID 34326374, 2021). "It has been reported that COL1A1 and COL1A2 are both overexpressed in gastric cancer, and a high COL1A1 and COL1A2 mRNA expression was suggested to be a prognostic factor predicting OS." (PMID 34283070, 2021). "Numerous studies have shown that COL1A2 is closely related to the prognosis of patients with gastric cancer 37, and lung and esophageal cancers." (PMID 34815785, 2021). "Previous article has verified silence of COL6A3 and COL1A2 can inhibit tumor cell proliferation, migration, and invasion in the gastric cancer." (PMID 33928021, 2021). "A study of gastric carcinoma showed that activation of the H19‐miR‐29a‐3p‐COL1A2 axis was positively correlated with M2 macrophage infiltration." (PMID 34598322, 2021). "High COL1A2 mRNA expression was positively correlated with poor overall survival time in patients with gastric cancer." (PMID 32525891, 2020). "Since miR-29b and miR-29c are known to be downregulated in GC, it is possible that the overexpression of COL1A2 observed in gastric tumor tissue is maintained in part by the disturbance in circHIPK3/miR-29b-c/COL1A2 axis, leading to gastric cancer progression." (PMID 32708088, 2020). "Expression of COL1A2 has been noted in gastric cancer and was positively correlated with degree of invasion and metastases." (PMID 31616464, 2019).